TNFSF9 (TNF superfamily member 9)
Diseases named in the same sentence as TNFSF9 in open-access papers (continued):
Sharing a sentence is not in itself a finding about the gene and the disease.
migraine (1 paper, 2008). "Further studies need to be performed with TNFSF7 and MO affected individuals and also other possible TNF receptor family homologues on C19p13, such as TNFSF9 (C19p13.3) and TNFSF14 (C19p13.3) should be tested for migraine involvement." (PMID 19018300, 2008).
myeloid leukemia (1 paper, 2022). A clonal proliferation of myeloid cells and their precursors in the bone marrow, peripheral blood, and spleen. "For example, genetically modified myeloid leukemia cell line K562 expresses IL-15, IL-18, and 4-1BBL (TNFSF9) on the surface of its EVs." (PMID 36405712, 2022).
pancreatic adenocarcinoma (1 paper, 2024). "The most significantly upregulated protein is the tumor necrosis factor ligand superfamily member 9 (TNFSF9), which participates in regulating immune cell infiltration in pancreatic adenocarcinoma." (PMID 39684519, 2024).
prostate carcinoma (1 paper, 2022). A carcinoma that arises from epithelial cells of the prostate gland. "The results showed that silencing the expression of DUSP1 and TNFSF9 promoted the growth and proliferation of the prostate cancer PC3 cells." (PMID 36142828, 2022). "This study demonstrates that HXL131 exhibited excellent anti-prostate cancer activity and inhibited the growth and metastasis of prostate cancer cells by regulating the expression of DUSP1 and TNFSF9." (PMID 36142828, 2022).
thyroid cancer (1 paper, 2022). "Using the TISIDB database, we demonstrated that ALDH1A1/A3/B1 had significant negative correlations with immune-stimulating genes, such as CD276, TMEM173, TNFSF9, CD70, TNFRSF25, and CD40 in thyroid cancer." (PMID 35280765, 2022).
tumor (142 papers, 2005 to 2026). "This study demonstrated that RBM15 enhanced PTX resistance in TNBC by promoting m6A methylation in TNFSF9 and inducing M2 polarization of tumor-associated macrophages." (PMID 40830812, 2025). "In other words, TNFSF9 regulated the M2 polarization of tumor-associated macrophages during TNBC progression." (PMID 40830812, 2025). "RBM15/TNFSF9 induced M2 polarization of tumor-associated macrophages and enhanced paclitaxel resistance in TNBC." (PMID 40830812, 2025). "Using mSigDB hallmarks which is a curated database of refined gene sets, we furthermore, found that high TNFSF9 expression is associated with higher enrichment score for several tumor-promoting hallmarks gene sets including inflammation, angiogenesis and EMT." (PMID 38191418, 2024). "TNFSF9 was mainly expressed in tumor-associated macrophages and upregulated in the CRC microenvironment." (PMID 35517502, 2022). "On this basis, we speculated that TNFSF9 may expedite the malignant progression of TNBC by enhancing the M2 polarization of tumor-associated macrophages (TAMs)." (PMID 40830812, 2025). "What’s more, through WB analysis of tumor tissues, we further verified the existence of a clear positive correlation between TNFSF9 and RBM15 in tumors." (PMID 40830812, 2025). "Mice that survived after initial implantation of CT-2A-FLuc-Tnfsf9 or 005-FLuc-Tnfsf9 cells were rechallenged with a second tumor (CT-2A-FLuc and 005-FLuc, respectively)." (PMID 40842154, 2025). "The combination of Tnfsf9 overexpression by tumor cells and rIL-12 nearly doubled (~70% versus 40%, respectively) the proportion of long-term survivors compared with Tnfsf9 overexpression alone." (PMID 40842154, 2025). "The results clarified that, compared to PTX-sensitive patients, the expression levels of RBM15 and TNFSF9 were abnormally high in the tumor tissues of PTX-resistant patients, and there was a relatively significant positive correlation between the two." (PMID 40830812, 2025). "The results revealed that either RBM15 or TNFSF9 mRNA were indeed highly expressed in the tumor tissues of PTX-resistant patients." (PMID 40830812, 2025). "The xenograft tumor models in nude mice were established to verify the impact of RBM15/TNFSF9 on the sensitivity of PTX-resistant TNBC cells to PTX in vivo." (PMID 40830812, 2025). "Considering the critical role of TNFSF9 in tumor immune suppression and immunotherapy, we studied the relationship between its expression levels and ER stress-related risk scores." (PMID 39119088, 2024). "Plasma B cell, CD8+ T cell, T follicular helper (TFH) cell, regulatory T (Treg) cell, and M1 Macrophage levels were significantly increased in the TNFSF9-high-expression tumor." (PMID 39000552, 2024). "Our previous work showed that bacteria-derived AI-2 was associated with tumour immunity in CRC patients through inducing tumour-associated macrophages and reducing CD4/CD8 ratio in a TNFSF9-dependent manner." (PMID 38725098, 2024). "Populations of tumor-infiltrating immune cells by TNFSF9 expression were examined using the CIBERSORT method." (PMID 39000552, 2024). "Among immunostimulators, CD276, PVR, TNFRSF14, TNFRSF25 and TNFSF9 were also negatively correlated with LAMP3 expression in some tumours." (PMID 38146591, 2024). "The expression level of TNFSF9 was also distinctly higher in tumor samples from high SPTBN1-expression UVM group compared to ones with low SPTBN1-expression level (Mann–Whitney U score = 245.0, p = 0.01)." (PMID 37013511, 2023). "Differential analysis showed that GNAI3, PCDH7, PSEN1 and TNFSF9 were highly expressed in tumor tissues, while ADM, CD69, SLC11A2 and TLR2 were opposite." (PMID 36117156, 2022). "Of these eight genes, four (GNAI3, PCDH7, PSEN1, TNFSF9) were highly expressed in tumor tissues and were associated with poor prognosis, while CD69, SLC11A2, and TLR2 were poorly expressed in tumor tissue and were associated with good prognosis." (PMID 36117156, 2022).
tumor (continued). "Cytokines secreted by tumor cells can regulate the polarization of macrophages, so we verified the effect of TNFSF9 knockdown on cytokine secretion of tumor cells by qPCR." (PMID 34517345, 2021). "The expression of TNFSF9 found on tumor cell lines is functional and has different functions in various types of cells." (PMID 34517345, 2021). "TNFSF9 (4-1BB/CD137) antibody favored the propagation of CD8+ tumor-infiltrating lymphocytes (TILs) from TNBC tumors, being capable of cytotoxic functions." (PMID 30728901, 2019). "Among these, the co-stimulatory receptor 4-1BB (CD137/TNFSF9) possesses an unequaled capacity for both activation and pro-inflammatory polarization of anti-tumor lymphocytes." (PMID 26106583, 2015). "Additionally, it influences tumor-infiltrating macrophages by driving their polarization toward the M2 phenotype through increased TNFSF9 expression via H3K18La." (PMID 39979245, 2025). "RBM15 targeted the N6-adenylate methylation (m6A) modification of TNFSF9, and overexpression of TNFSF9 could reverse the tumor-suppressing effect of silencing RBM15 on PTX-resistant TNBC cells in vitro and transplanted tumors in vivo." (PMID 40830812, 2025). "Furthermore, the positive correlation between RBM15 and TNFSF9 in the tumor tissues of PTX-resistant patients was also proved by Spearman’s correlation analysis." (PMID 40830812, 2025). "In addition, we examined the influence of RBM15/TNFSF9 on the polarization state of macrophages within the TNBC tumor microenvironment, further elucidating the molecular mechanisms of PTX resistance in TNBC." (PMID 40830812, 2025). "The effect of RBM15/TNFSF9 on PTX sensitivity in vivo was verified by xenograft tumor experiments." (PMID 40830812, 2025). "Additionally, WB analysis demonstrated that when RBM15 was silenced in MDA-MB-231/PTX cells, the protein level of RBM15 was down-regulated in mouse tumor tissues, accompanied by a concomitant decrease in TNFSF9 levels." (PMID 40830812, 2025). "A schematic summary of the proposed hypothesis illustrates how Tnfsf9 treatment enhances rIL-12 therapy by promoting interactions among distinct immune cell populations, stimulatory ligands, and receptors at the tumor site." (PMID 40842154, 2025). "Our results further suggested that pathogenic bacteria, like Fusobacterium nucleatum, may interact with CRC cells and modify the tumor immune environment by TNFSF9, finally facilitating the tumor development." (PMID 38369542, 2024). "Finally, we revealed that Fusobacterium nucleatum modified the tumor immune environment by TNFSF9 gene expression." (PMID 38369542, 2024). "Specifically, the downregulation of TNFSF9 by Fusobacterium nucleatum could modify the tumor immune environment, facilitating tumor progression by impairing the immune response." (PMID 39273009, 2024). "Therefore, tumors with high TNFSF9 expression were characterized by higher tumor purity and higher immune cell infiltration." (PMID 39000552, 2024). "tumor cells could escape immunosurveillance via interacting with immune modulator markers, such as TNFSF9, CTLA4 and PDCD1, which are known as important molecules for cancerigenesis or cancer immunotherapy." (PMID 37013511, 2023). "In addition, CD48, CTLA4, HHLA2, TNFSF9, and TNFSF15 were elevated in high-risk group, suggesting that the high-risk group are more likely to show immunosuppressive phenotype in tumor microenvironment." (PMID 37903974, 2023). "This correlated with an increase in the expression of genes encoding TNFSF9 (tumor necrosis factor ligand superfamily member 9), as noted in tumor-associated macrophages." (PMID 36296244, 2022). "Further studies are now required to examine these effects using primary cells from patients with chronic lymphocytic leukemia (CLL) and to determine in animal models whether 4-1BBL/TNFSF9 up-regulation contributes to HDACi-induced anti-tumor effects in vivo." (PMID 19759901, 2009).
tumor (continued). "In summary, this study has unveiled an important finding: RBM15 may exacerbate the resistance of TNBC to PTX and accelerate the progression of TNBC by regulating the m6A methylation modification of TNFSF9 mRNA and inducing M2 polarization of TNBC tumor-associated macrophages." (PMID 40830812, 2025). "However, after silencing RBM15 and then overexpressing TNFSF9, the protein level of TNFSF9 in tumor tissues showed a significant rebound trend, confirming that RBM15 could also targeted and regulated TNFSF9 in vivo." (PMID 40830812, 2025). "However, when Tnfsf9 expression at the tumor was combined with rIL-12, survival outcomes were similar across genotypes: 69.2% of Il12b+/+ mice and 63.6% of Il12b−/− mice survived beyond 50 days, indicating that exogenous rIL-12 can compensate for the absence of endogenous IL-12." (PMID 40842154, 2025). "A modified analysis of the NUGC-3 tumor samples showed that PC14586 administration in vivo led to changes in the expression of immune and inflammatory signaling–associated genes and gene sets (TNFSF9, CSF2, IL1A, GDF15, and TNFA signaling and inflammatory response)." (PMID 39945593, 2025). "In general, patients with high TIDE scores are less likely to respond to immune checkpoint inhibitor (ICI) monotherapy (CTLA4 inhibitors or PD-1 inhibitors), and the predominance of high TIDE scores in the TNFSF9-high tumor suggests that ICI monotherapy may be less effective." (PMID 39000552, 2024). "Therefore, we hypothesized that TNFSF9 may have individual differences in its effect on tumor cells, showing both inhibitory and activate effects." (PMID 34517345, 2021). "Simultaneously, differentiation- and immune-activating signals such as CSF1, TNFSF9, KITLG, EHF, and CHRM1 were downregulated, potentially modulating tumor immune escape and proliferation in a context-dependent manner." (PMID 41009714, 2025). "Thus, TNFSF9 may be a tumor suppressor, deemed as a therapeutic target for HCC." (PMID 36969014, 2023). "In this study, TNFSF9 was up-regulated in the HXL131-treated PC3 cells, thus acting as a tumor suppressor." (PMID 36142828, 2022). "For example, PHLDA1 was positively correlated with the infiltration levels of a variety of immunocompetent tumor-infiltrating cells, including Act CD4, CD56dim, and Act DC and 23 types of immune promoters, including IL6, NT5E, and TNFSF9." (PMID 36142223, 2022). "With increased tumor PD-L1, expression of activation and cytotoxicity marker genes, including IFNG, TNFSF9, TNFSF14, CSF2, and IL2, were downregulated in both Tnull and TCR-TMART-1, consistent with results of cytokine secretion assays." (PMID 33754038, 2021). "The cross-linking of TNFSF9 and TNFRSF9 on liver cancer cells HepG2 triggers the production of interleuukin-8 (IL-8) by tumor cells." (PMID 34517345, 2021). "Based on the intersection of TNF superfamily signature between human BC tissues and cell lines to exclude the tumor heterogeneity, both TNBC tissues and cell lines dominantly expressed CD70 and TNFSF9." (PMID 30728901, 2019). "The TNFR superfamily proteins are expressed by antigen-presenting cells (APC) or tumor cells, including TNFSF4 (OX40L), TNFRSF5 (CD40), TNFSF7 (CD70), TNFSF9 (CD137L), TNFRSF14 (HVEM), and TNFSF18 (GITRL)." (PMID 30609841, 2019). "In Il12b+/+ mice that did not receive rIL-12, Tnfsf9 expression by the tumor cells significantly extended median survival by 27 days compared with CT-2A-FLuc-null control condition." (PMID 40842154, 2025). "Tumor-infiltrating effector CD8 T cells were identified as drivers of LAG3, TNFSF9, and HAVCR2 overexpression, which suggests effector CD8 TILs are activated and exhausted relative to circulating leukocytes, a finding that is consistent with reports across multiple human tumor types." (PMID 39932553, 2025). "We demonstrated that 4–1BBL overexpression at the tumor site increased the survival of rIL-12-treated animals, and we could recapitulate these results with AAV vector-mediated Tnfsf9 gene therapy." (PMID 40842154, 2025).
tumor (continued). "Additionally, we conducted a WB assay on the patients’ tumor tissues, which also indicated that the expression of RBM15 and TNFSF9 were drastically upregulated in the PTX-resistant in contrast to the PTX-sensitive group." (PMID 40830812, 2025). "However, in the mice group with overexpression of TNFSF9 in the stably silenced RBM15 cell line, despite PTX treatment, the tumor growth rate, and weight still increased." (PMID 40830812, 2025). "However, when TNFSF9 was overexpressed, the therapeutic effect of PTX on the tumor was obviously reduced." (PMID 40830812, 2025). "Comparing non-metastatic tumor cluster 1 versus either cluster 12 or 14, we not only found lower expression of TNFSF9 (encoding 41BBL) but also higher levels of SIAH1 which is an E3 ligase that was found to be downregulated during TGFB-induced EMT." (PMID 38191418, 2024). "In addition, we analyzed the population of immune cells infiltrating tumor cells using TIMER, finding that B cells, CD8+ T cells, and myeloid dendritic cells were significantly increased in the high-TNFSF9-expression group." (PMID 39000552, 2024). "Importantly, we identified several lymphocyte activation ligands that were significantly upregulated on Ccr7_DC.2 versus other tumour CCR7+ DC states and Kaede-red dLN CCR7+ DCs, such as Il12b, Tnfsf4, Tnfsf9, Cd70 and Pvr." (PMID 38267413, 2024). "Notably, TNFSF9 (CD137L) is a key activating immune checkpoint molecule, and its agonist, in combination with PD-L1, can potently activate and expand tumor-specific cytotoxic T cells, thereby enhancing their inhibitory and lethal effects on tumors." (PMID 39872533, 2024). "Given the potential of TLR8 and TNFSF9 as new targets for cancer immunotherapy, how specific HLA-I genotypes influence their expression in tumor microenvironment and the role of HLA-A02+B62+B44− in treatment outcomes of related drugs targeting TLR8 or TNFSF9 deserve to be further studied." (PMID 37026827, 2023). "We found that the costimulatory molecules TNFSF15 and TNFSF9 were overexpressed in the siGPX4 group, suggesting that GPX4 knockdown could inhibit tumor angiogenesis." (PMID 37649598, 2023). "TNFSF9, CD276, CD40, CD274, and CD44 expression was downregulated in cluster 6 (hypoxic tumor)." (PMID 36685583, 2022). "First, PHLDA1 was positively correlated with the infiltration levels of a variety of immunocompetent tumor-infiltrating cells, including Act CD4, CD56dim, and Act DC, and 23 types of immune promoters, including IL6, NT5E, and TNFSF9." (PMID 36142223, 2022). "Curiously, TNFSF9 (4-1BB-L) was present at a surprisingly high abundance in ACC when compared to that of other TCGA tumor types, but not its receptor TNFRSF9 (4-1BB), which was present mainly on CD8+ T cells." (PMID 34194394, 2021). "Proteins OX-40 ligand (OX-40 L/TNFSF4/CD134L/CD252) and 4-1BB ligand (4-1BBL/TNFSF9/CD137L) regulate effector cytotoxic T-cell (CTL) activity while programmed death ligand-1 (PD-L1) exhibits immunosuppressive effects, allowing the tumor to escape immune destruction." (PMID 30064416, 2018). "The observed positive correlation between PYGB and TNFSF9 (also known as 4-1BBL), a co-stimulatory molecule that enhances T-cell proliferation and survival, suggested that PYGB might be involved in modulating T-cell responses within the tumor microenvironment." (PMID 40458414, 2025). "Next, we tested whether enhancing co-stimulation with Tnfsf9 in absence of endogenous IL-12 could drive tumor regression, given that IL-12 is strongly suppressed at the TME in GB patients." (PMID 40842154, 2025). "Interestingly, host-derived IL-12 did not appear to play a major role in the anti-tumor response to rIL-12 monotherapy, but it was critical for the efficacy of Tnfsf9 monotherapy and the combination treatment." (PMID 40842154, 2025).
tumor (continued). "We hypothesize that this might be due to transgene instability in tumor cells, promoter inactivity or silencing, or potential overgrowth by small numbers of non-expressing Tnfsf9 GB cells, rather than an effect of rIL-12 treatment." (PMID 40842154, 2025). "In addition, under hypoxic conditions, tumor necrosis factor superfamily member 9 (TNFSF9) expression is upregulated through a histone lactoylation-dependent mechanism, inducing polarization of M2-type macrophages and leading to malignant progression of tumor cells." (PMID 40703527, 2025). "by using TIMER 2.0 online tool and adjusting tumor purity, we found that SPTBN1 expression had negative correlations with the expression levels of TNFSF9 (R =-0.238, p = 2.31E-07), PDCD1 (R =-0.191, p = 3.81E-05) and CTLA4 (R =-0.16, p = 5.67E-04) in KIRC (revised_Figure 6B)." (PMID 37013511, 2023).